HIF1A (hypoxia inducible factor 1 subunit alpha)
Diseases named in the same sentence as HIF1A in open-access papers (continued):
Sharing a sentence is not in itself a finding about the gene and the disease.
anemia (continued). "The resultant anemia aggravates tissue hypoxia, activating hypoxia-inducible factor-1α (HIF-1α)." (PMID 40687061, 2025). "Agents with greater HIF-2α selectivity may achieve more targeted anemia correction with fewer systemic effects, whereas broader HIF-1α activation could explain signals related to vascular or metabolic complications." (PMID 41239296, 2025). "HIF1α inhibitors are also studied, albeit only for therapy of cancer, anemia, and vascular disease." (PMID 39543383, 2024). "Supporting these physiological approaches to activate HIF1α by HIF-prolyl hydroxylase inhibitors or AMPK by metformin might prevent anemia and protect from mitochondrial dysfunction." (PMID 37760862, 2023). "In the tumor microenvironment, the increased platelets and the presence of cancer-associated anemia can induce angiogenesis by stimulating vascular endothelial growth factor (VEGF) and upregulating hypoxia inducible factor-1α (HIF-1α), which has significant role in cancer progression." (PMID 34751228, 2021). "For this purpose, the siRNA-based induction of renal HIF-1α may be a promising approach for treating anemia in CKD patients." (PMID 31332228, 2019). "Finally, the primary therapeutic target for treatment of anemia is HIF2α, while many of these other interactions are with HIF1α." (PMID 29382128, 2018). "Some researchers have revealed that Herba Leonuri obviously increased the numbers of erythrocyte, attenuated the levels of EPOR and IL6, inhibited HIF-1α expression, and consequently improved the anemia, which supported its crucial role in the improvement of anemia." (PMID 29551975, 2018). "Since LDHA expression is under the control of HIF1α transcription factor, it could be involved in the response of immature erythroid progenitors to anemia." (PMID 28027290, 2016). "Hence, we used ANCOVA and found that for tumor tissue both HIF1α (p < 0.001) and anemia (p = 0.014) significantly affected Nampt/PBEF/visfatin expression." (PMID 26075243, 2015). "Hence, the proposed mechanism suggests that iron deficiency anemia might indirectly regulate LRG1 expression, possibly by upregulating HIF-1α expression, which regulates direct targets of LRG1 promoter including IL-6 and TNFα." (PMID 37513518, 2023). "Besides, to evaluate whether XSHG had the anti-anoxia effects, the expression of HIF-1α was determined in anemia rats." (PMID 29551975, 2018). "However, in nontumor tissue, the association with anemia lost significance (p = 0.718) when Nampt/PBEF/visfatin correlation with HIF1α (p < 0.001) was accounted for." (PMID 26075243, 2015). "The HIF-1α activator Roxadustat (FG-4592), a HIF hydroxylase inhibitor, is currently being investigated for anemia treatment." (PMID 38600597, 2024). "While the exact relationship between LRG1 and iron deficiency anemia remains largely unclear, one hypothesis is based on its involvement in the regulation of HIF-1α protein expression, because it has been shown that iron deficiency increases HIF-1α which regulates VEGF." (PMID 37513518, 2023). "We evaluated the effects of TBN on HIF-2α and HO-1 in STZ-induced DKD anemia rats and the effects of TBN on HIF-1α and HIF-2α in CDDP-induced C57BL/6J anemic mice." (PMID 36324690, 2022). "However, it is unclear whether renoprotection was mechanistically linked to the activation of HIF-1α or, rather, of the HIF-2α isoform, which is a key regulator of renal erythropoiesis and a potential new target for the treatment of anemia in chronic kidney disease." (PMID 34572324, 2021). "Collectively, the action mechanisms for treating anemia of XSHG were attributed to the activation of coenzyme A biosynthesis, inhibition of sphingolipid metabolism and suppression of HIF-1α pathway." (PMID 29551975, 2018). "In anemia, the lack of adequate oxygen supply to brain tissue triggers a cascade of compensatory mechanisms, such as the activation of HIF-1α." (PMID 40486649, 2025).
anemia (continued). "HIF-1α agonists, such as small molecule hypoxia-inducing factor-prolyl hydroxylase inhibitor GSK1278863, used in clinical trials to treat anemia caused by chronic kidney disease without serious adverse effects." (PMID 32587244, 2020). "Yet, in the logistic regression, of all the factors investigated, Nampt/PBEF/visfatin upregulation in addition to HIF1α was an anemia predictor in CRC patients (data not shown)." (PMID 26075243, 2015). "Immunofluorescence staining revealed that renal HIF-1α and HIF-2α expression was significantly higher in classes II–IV than class I. Thus, the addition of glomerular pathology classification increases the value of anemia status for the prediction of the progression to ESRD." (PMID 35188068, 2022).
heart failure (60 papers, 2013 to 2026). Inability of the heart to pump blood at an adequate rate to meet tissue metabolic requirements. "Tafazzin-deficient mice hearts display reduced HIF-1α levels and undergo maladaptive hypertrophy with heart failure in response to pressure overload challenge." (PMID 30332638, 2018). "This study aimed to evaluate the hypothesis that there is an early change and intensification of HIF-1α, glucose metabolism, and the association between these variables during the progression from hypertrophy to heart failure (HF)." (PMID 37047174, 2023). "Our hypothesis was confirmed as there was an early change and intensification in glucose metabolism, alteration in HIF-1α, and an association between data during the progression from hypertrophy to heart failure." (PMID 37047174, 2023). "Furthermore, repetitive seizures and/or status epilepticus also activate HIF-1α and induce P-gp overexpression in heart, which appears to be associated with heart failure and sudden unexpected death in epilepsy (SUDEP)." (PMID 32256321, 2020). "HIF-1α deficiency will accelerate the onset of heart failure in TAC after 3 weeks." (PMID 26223692, 2015). "Consequently, HIF-1α dysregulation may contribute to various sympathetic abnormalities underlying cardiac pathologies, including heart failure and sudden cardiac death." (PMID 37072781, 2023). "The results showed that the expression levels of HIF-1α, IL10, PAD4, ACTG1, SOD2, and GAPDH were higher in heart failure patients with Qi deficiency and blood stasis syndrome compared to the HP group." (PMID 40671145, 2025). "Further research is needed to confirm our findings and to elucidate the potential role of HIF-1α in TAC-induced heart failure." (PMID 41515999, 2025). "They found increased expression of HIF-1α in the hearts of late-stage heart failure patients, suggesting that prolonged chronic upregulation of HIF-1α has a deteriorating effect on the heart." (PMID 38164358, 2024). "TF65, in particular, promotes apoptosis in heart failure and is required for the pressure overload compensation by cardiomyocytes; in its absence, cardiomyocytes fail to increase the expression of HIF1A (YN), the TF65 target protein." (PMID 38326862, 2024). "As we described, transgenic mice forcibly expressing HIF-1α spontaneously exhibited signs of heart failure such as thickened cardiac septa and reduced shortening fraction over time." (PMID 37108502, 2023). "HIF-1α plays a protective role in various cardiovascular diseases, such as ischemic reperfusion and heart failure." (PMID 37723445, 2023). "Four weeks after coronary ligation leads to proper activation of HIF-1α signaling is essential for myocyte survival after myocardial ischemia and heart failure." (PMID 36843948, 2023). "NF-κB can be activated in the presence of oxidation stress which will induce Reactive Oxygen Species (ROS) and affect the activation of NF-κB and HIF-1α in hypoxic conditions due to microorganism infection and doxorubicin induction in cardiac failure." (PMID 38058621, 2023). "Although studies on HIF-1α in cardiovascular disease suggested a cardioprotective role, studies by Tang and Shyu revealed that HIF-1α also contributed to I/R injury in MI or volume-overloaded heart failure." (PMID 35396503, 2022). "Previous study showed that Hif-1α+/− mice developed more severe heart failure after TAC compared with wild type mice, due to a decrease in SR Ca2+ content of cardiomyocytes." (PMID 36407000, 2022). "The regulatory effect of miR-221-3p on the expression of HIF-1α is consistent with a recently published study, which demonstrated that HIF-1α was the target gene of miR-221-3p in patients with heart failure and antagomiR-221-3p increased HIF-1α expression." (PMID 34497517, 2021). "Studies have also shown that HIF-1α is responsible for recruiting M1 macrophages that release TNF-α in patients with heart failure." (PMID 34497517, 2021).
heart failure (continued). "Here, we demonstrate that in NHPs, amylin deposition in heart failure (HF) contributes to cardiac dysfunction via activation of HIF1α and PFKFB3 signaling." (PMID 33580152, 2021). "For example, a study reported that increasing the expression of cardiac HIF-1α resulted in aggravated heart failure." (PMID 33135539, 2020). "Carvedilol, a β-blocker to treat heart failure, reversed the abnormal regulation of HIF1A and VEGF28." (PMID 31221962, 2019). "HIF-1α plays a critical role in the cellular response to hypoxia in many cardiovascular diseases 1, 2, 8, 9, 10, and decreased HIF-1α activation accelerates the progression into heart failure in genetic mouse models." (PMID 30175272, 2018). "We therefore investigated MIF and HIF-1α expression in myocardial samples from patients with heart failure and show different expression levels depending on the underlying type of cardiomyopathy." (PMID 29027966, 2017). "A previous study has showed that gelsolin is an important contributor to heart failure progression through novel mechanisms of HIF-1α and DNase I activation and downregulation of antiapoptotic survival factors." (PMID 23533533, 2013). "For this purpose, we examined whether SIL exerts its cardioprotective effects through the modulation of HIF-1α-mediated glycolysis, with the goal of identifying novel therapeutic targets for post-MI heart failure management." (PMID 40944191, 2025). "However, as pressure overload-induced RVR progresses to heart failure, increased HIF-1α expression exacerbates the condition." (PMID 38164358, 2024). "However, there are gaps regarding the behavior of key proteins in the glycolytic pathway and HIF-1α during the transition from hypertrophy to heart failure (HF)." (PMID 37047174, 2023). "Gene–disease association information were as follows: HIF1A is associated with heart failure and cardiac hypertrophy; IL6 is associated with heart failure and cardiomyopathy; PTGS2 is associated with aortic aneurysms, heart failure, cardiac arrhythmias, cardiomyopathy, and CVD." (PMID 37283588, 2023). "It downregulates HIF1α in the myocardium of volume-overloaded heart failure." (PMID 35860430, 2022). "In summary, YHR may provide cardioprotective effects in heart failure through inhibiting the Keap1/Nrf2/HIF-1α apoptosis pathway." (PMID 33739243, 2021). "This evidence suggested that the upregulation of HIF-1α might be a potential therapeutic option for treating heart failure post AMI." (PMID 32626732, 2020). "For example, the role of HIF1A in a TAC model to mimic heart failure produced disparate results." (PMID 31221962, 2019). "The HIF-1α level may become a prognostic biomarker of heart failure; however; this potential role needs to be validated by means of further prospective studies in the future." (PMID 26223692, 2015). "In pressure overload-induced heart failure, HIF-1α can protect heart failure." (PMID 26223692, 2015). "Consequently, Hif-1α is crucial as the main therapeutic target for SIL in managing heart failure." (PMID 40944191, 2025). "In addition, stem-like genes such as CTNNB1, MYC, and HIF1A may also attenuate heart failure after cardiomyopathy." (PMID 40717095, 2025). "Consequently, inhibition of neddylation leads to accumulation of HIF1α proteins and persistent HIF1α signaling, which represses fatty acid utilization in late gestational and postnatal heart, leading to defects in CM maturation and eventually heart failure." (PMID 36662623, 2023). "The present study shows that SIL exerts cardioprotective effects by modulating the HIF-1α-glycolytic pathway, leading to the downregulation of key glycolytic enzymes (GLUT1, PFKFB3, LDHA) and the restoration of metabolic homeostasis in heart failure." (PMID 40944191, 2025).
heart failure (continued). "MiR-221-3p suppresses angiogenesis in endothelial cells by targeting HIF-1α, with evidence showing that blocking miR-221-3p enhances cardiac function in mice with transverse aortic constriction (TAC)-induced heart failure." (PMID 41409744, 2025). "Further elucidating the cellular and molecular mechanisms of HIF-1α in the pathogenesis of HPH will provide new evidence for the prevention and treatment of right ventricular remodeling and heart failure induced by pressure overload." (PMID 38164358, 2024). "By knowing the effect of DOX on changes in HIF-1α expression, it can be used as an alternative combination of DOX treatment and can prevent possible cardiotoxic effects in the form of heart failure." (PMID 35340325, 2022). "In this study, AK4 and HIF-1a showed a downward trend, while Nrf2, SOD, and CytC showed a significant downward trend, indicating that oxidative stress played a crucial role in heart failure." (PMID 33362553, 2020). "It was observed that HIF-1α, the main inducer of VEGF synthesis, also plays an important role in transmural angiogenesis in heart failure in addition to the effects of VEGF on thrombi." (PMID 32421278, 2020). "In utero exposure to caffeine also reportedly predisposes to increased adult body fat composition and adult heart failure, possibly through inhibition of A1AR and HIF1α activity." (PMID 24533117, 2014). "Third, our data are just descriptive and do neither give a mechanistical insight into the role of the HIF-1α/MIF axis in heart failure nor provide data on outcome and prognosis." (PMID 29027966, 2017). "Since digoxin, a cardiac glycoside used in the treatment of atrial fibrillation and heart failure, is also known to inhibit HIF-1α protein synthesis, we used this compound to pharmacologically suppress HIF-1α and analyze the effects on growth and invasion in uveal melanoma lines." (PMID 25166211, 2014). "Thus, the P2X7R-mediated HIF-1α/VEGF pathway may represent a novel approach to stimulating angiogenesis and preventing heart failure in ischemic heart disease." (PMID 41295364, 2025). "The lack of HIF-1α can accelerate the progression of heart failure caused by stress overload, and increasing HIF-1α expression can enhance myocardial autophagy and delay heart failure." (PMID 37723445, 2023). "Although there are investigations that have shown increased HIF-1α in hypertrophy related to heart failure, to our knowledge no other studies have systematically evaluated HIF-1α behavior during the different phases of cardiac remodeling evolution due to overload mechanics." (PMID 37047174, 2023). "The inability to stabilize HIF1α and to maintain the expression VEGF and other angiogenic growth factors may contribute to vascular rarefaction during prolonged phases of hypoxia and promote the transition toward heart failure." (PMID 30895179, 2019). "To date, no studies exist that report on the HIF-1α/MIF axis in heart failure." (PMID 29027966, 2017).
iron deficiency (59 papers, 2009 to 2026). "Iron deficiency upregulates hepcidin and hypoxia-inducible factor 1α (HIF1α), regulating, and promoting the transcription of fibroblast growth factor 23 (FGF-23), a hormone derived from osteocytes, regulating phosphate, and vitamin D homeostasis." (PMID 41445550, 2025). "Experimental models have shown that iron deficiency can elevate pulmonary artery pressure, promote right ventricular hypertrophy and vascular remodeling, and upregulate HIF1α, HIF2α, and STAT3 signaling pathways — changes that are reversible with iron therapy." (PMID 41451092, 2025). "Iron deficiency upregulates furin, a proprotein convertase that cleaves iFGF-23, by stabilizing HIF1-α, thereby leading to cleavage of FGF-23 into C-terminal cleavage fragments (c-FGF-23)." (PMID 39684548, 2024). "Studies have demonstrated a notable decrease in hepcidin in the liver in a murine model of iron deficiency, accompanied by a significant increase in HIF-1α levels." (PMID 39109237, 2024). "Several studies have identified the molecular mechanisms involved, showing that inflammation or iron deficiency induces HIF-1α and that the binding of HIF-1α increases its synthesis in osteogenic cells." (PMID 39684548, 2024). "The protein level of HIF1α was found to be elevated in cases of iron deficiency, while the protein level of Sp1 remained unchanged; however, the phosphorylation level of Sp1 showed an increase." (PMID 39228402, 2024). "Transgenic mice lacking HIF-1α no longer exhibit down-regulation of hepcidin in the liver following iron deficiency, indicating the pivotal role of HIF-1α in governing iron homeostasis and hepcidin regulation." (PMID 39109237, 2024). "It has been stated that iron deficiency increases HIF-1α protein expression, which upregulates the expression of IL-6 and TNFα." (PMID 37513518, 2023). "Iron deficiency has also been shown to increase HIF-1α expression, with subsequent regulation of VEGF." (PMID 37513518, 2023). "Overall, these previous reports indicate that both LRG1 and iron deficiency are implicated in regulating the HIF-1α pathway." (PMID 37513518, 2023). "Immunoblot analysis showed cellular HIF1α protein accumulation during DFO-mediated iron deficiency, and a reduction of HIF in WT cells provided holo-Tf repletion." (PMID 36650133, 2023). "The induction of HIF1α in osteoblasts and osteocytes, in response to iron deficiency or hypoxia, increases FGF23 production." (PMID 36895836, 2023). "Inflammation and systemic iron deficiency cumulatively enhance gene expression of ileal mucosal HIF1A and TFRC, where circulating free iron negatively associates with TFRC expression." (PMID 35755436, 2022). "In this study, we show a location-specific mucosal transcriptional response to inflammation and iron deficiency of HIF1α-target genes (particularly of TFRC) in intestinal mucosa of patients with IBD." (PMID 35755436, 2022). "The effect of inflammation or iron deficiency is mediated by an increase in hypoxia-inducible factor α (HIF1α) abundance or stabilization." (PMID 36246903, 2022). "Collectively, these findings would lead to higher circulation levels of iFGF23 in a setting of increased expression of HIF1α by either iron deficiency or hypoxia." (PMID 35629904, 2022). "In response to iron deficiency or hypoxic conditions, the protein expression of hypoxia-inducible factors, including HIF-1α and HIF-2α, is significantly elevated, and these proteins are recruited to the promoter of TfR1, thereby increasing TfR1 transcription." (PMID 34518441, 2021). "In the mouse model used in this study, 6 weeks of restriction of dietary iron resulted not only in systemic iron deficiency but also in cardiac hypoxia evidenced by the induction of HIF-1α expression." (PMID 33553263, 2020). "Absence of Gaa impairs the acidification of a large proportion of lysosomes, and fibroblasts obtained from these mice show iron deficiency and HIF-1α accumulation." (PMID 31793879, 2019).